ICAM4 (intercellular adhesion molecule 4 (Landsteiner-Wiener blood group))
Description:
Functions as a receptor ligand for the monocyte/macrophage-specific ITGAX:ITGB2 integrin complex and mediates erythrophagocytosis. Receptor ligand of the platelet-specific ITGA2B:ITGB3 integrin complex involved in heterotypic cell-cell adhesion between erythrocytes and activated platelets. In vitro, is also a receptor ligand of multiple integrin receptors complexes such ITGAL:ITGB2, ITGAM:ITGB2, ITGA5:ITGB1, ITGA5:ITGB3 and ITGA5:ITGB5 integrin complexes.
Synonyms: CD242; LW
Tractability: Antibody: UniProt places it where antibodies can reach, with high confidence; its Gene Ontology location is reachable by antibodies, with high confidence; UniProt predicts a signal peptide or a membrane-spanning region.
Gene: Protein-coding gene on chromosome 19 (10,286,955 to 10,288,522, forward strand). Ensembl gene ENSG00000105371.
Subcellular location: Cell membrane (Isoform Long); Secreted (Isoform Short); Cell membrane
Pathways (Reactome):
Extracellular matrix organization: Integrin cell surface interactions
Immune System: Immunoregulatory interactions between a Lymphoid and a non-Lymphoid cell
Gene Ontology:
Molecular function: receptor ligand activity; integrin binding
Biological process: cell-cell adhesion mediated by integrin; heterotypic cell-cell adhesion; leukocyte cell-cell adhesion; phagocytosis; cell adhesion; cell adhesion mediated by integrin; cell-cell adhesion; signal transduction
Cellular component: membrane; plasma membrane; extracellular region
Genetic constraint (gnomAD): Loss-of-function variants: 16 observed, 19.27 expected, observed/expected ratio (o/e) 0.83, 90% interval 0.56 to 1.26. The upper end of that interval is the gene's LOEUF score, 1.26, which puts it in group 5 of 6, group 1 being the genes least tolerant of losing a copy. Missense variants: 338 observed, 378.71 expected, observed/expected ratio (o/e) 0.89, 90% interval 0.82 to 0.98. Synonymous variants: 163 observed, 169.58 expected, observed/expected ratio (o/e) 0.96, 90% interval 0.85 to 1.1.
Homologues: Orthologues: macaque ICAM4 (89% identical), dog ICAM4 (72% identical), pig ICAM4 (68% identical), mouse Icam4 (66% identical), rat Icam4 (60% identical), chimpanzee ICAM4 (55% identical). Paralogues in human: ICAM5 (28% identical), ICAM1 (26% identical), ICAM3 (26% identical), ICAM2 (23% identical).
Diseases named in the same sentence as ICAM4 in open-access papers:
ICAM4 is named in the same sentence as 26 diseases in open-access papers, as found by Europe PMC text mining. Sharing a sentence is not in itself a finding about the gene and the disease. The quoted sentences say what the papers report.
sickle cell disease (5 papers, 2017 to 2025). Sickle cell anemias are chronic hemolytic diseases that may induce three types of acute accidents: severe anemia, severe bacterial infections, and ischemic vasoocclusive accidents (VOA) caused by sickle-shaped red blood cells obstructing small blood vessels and capillaries. "HU is also known for modulating the expression of several adhesion molecules on RBCs, but evidence shows that it contributes by reducing the expression of molecules such as α4β1, CD36, VLA-4, and ICAM-4 of erythroid cells from sickle cell disease patients." (PMID 40507944, 2025). "The best documentation of a pathophysiological role for ICAM4 in human disease is in sickle cell disease, where it contributes to red cell adhesion to endothelial cells and the development of vaso-occlusion, the hallmark of that disease." (PMID 29297313, 2017). "Abnormal adhesion of RBCs was first observed in sickle cell anemia involving vascular cell adhesion molecule (VCAM)-1, α4β1, Lu/BCAM, and intercellular adhesion molecule (ICAM)-4." (PMID 32727002, 2020).
atherosclerosis (2 papers, 2024). A disease characterized by the build-up of fatty material and calcium deposition in the arterial wall resulting in partial or complete occlusion of the arterial lumen. "This is supported by upregulation of SELE, ICAM4, and SLAMF4 with involvement in leukocyte activation, adhesion, and general immune regulation and positive regulation of MAPK signalling, all of which have been implicated in atherosclerosis pathophysiology." (PMID 39408698, 2024).
breast carcinoma (2 papers, 2017 to 2022). "ICAM1, ICAM4, and ICAM5 are associated with breast cancer susceptibility loci as indicators of disease severity." (PMID 35341150, 2022).
Arterial thrombosis (1 paper, 2017). The formation of a blood clot inside an artery. "ICAM4 may also contribute to other intravascular processes, such as both venous and arterial thrombosis, due to its ability to interact with both activated platelets and leukocytes." (PMID 29297313, 2017).
cardioembolic stroke (1 paper, 2023). "We found positive associations of genetically determined plasma ICAM-4 with the risks of ischemic stroke and cardioembolic stroke." (PMID 37041579, 2023). "Hence, we explored the associations of genetically determined ICAM-4 levels and the risks of ischemic stroke and its subtypes (cardioembolic stroke [CES], large artery stroke [LAS], and small vessel stroke [SVS]) via a two-sample MR study." (PMID 37041579, 2023).
gastroschisis (1 paper, 2024). Gastroschisis is marked by viscera protruding, without a covering sac, from the fetal abdomen on the right lateral base of the umbilicus. "Padula investigated 75 genetic variants in 20 genes and found 11 gastroschisis-associated variants in NOS3, ADD1, GNB3, ICAM1, ICAM4, ICAM5, and NAT1 genes." (PMID 39728087, 2024).
ischemic stroke (1 paper, 2023). A stroke disorder caused by obstruction of blood flow to the brain, due to thrombotic (local blood clot formation) or embolic (due to a blood clot or other material traveling from another site) event. "We conducted a systematical MR study to investigate the associations of genetically determined ICAM-4 levels and the risks of ischemic stroke and its subtypes." (PMID 37041579, 2023). "Further studies are warranted to explore the detailed mechanism underlying the association of ICAM-4 with ischemic stroke and CES." (PMID 37041579, 2023). "Herein, we performed a two-sample Mendelian randomization (MR) analysis to investigate the associations of genetically determined plasma ICAM-4 with the risks of ischemic stroke and its subtypes." (PMID 37041579, 2023). "The present MR study was the first to provide population-based evidence for the associations of ICAM-4 levels with the risks of ischemic stroke and its subtypes from a genetic point of view." (PMID 37041579, 2023). "Further studies are needed to verify our findings and explore the detailed mechanism underlying the detrimental effects of ICAM-4 on the risk of ischemic stroke." (PMID 37041579, 2023). "We used the inverse-variance weighted method followed by a series of sensitivity analyses to evaluate the associations of genetically determined ICAM-4 with the risks of ischemic stroke and its subtypes." (PMID 37041579, 2023). "We found positive associations of genetically determined high plasma ICAM-4 levels with the risks of ischemic stroke and CES." (PMID 37041579, 2023). "In this MR study, genetically determined high ICAM-4 levels were observed to be associated with the increased risk of ischemic stroke, suggesting that it might be a promising predictive marker for ischemic stroke." (PMID 37041579, 2023). "However, to date, there is limited population-based research on the effect of ICAM-4 in the risk of ischemic stroke." (PMID 37041579, 2023). "Therefore, it has been suggested that ICAM-4 may be associated with the development of thrombosis and ischemic stroke, but the population-based evidence is limited so far." (PMID 37041579, 2023). "Therefore, we speculated that elevated ICAM-4 levels were significantly associated with increased risks of ischemic stroke and CES via mediating aggregation and abnormal adhesion of inflammatory cells, macrophages, and platelets." (PMID 37041579, 2023). "Future studies are needed to explore the detailed mechanism and investigate the targeting effect of ICAM-4 on ischemic stroke." (PMID 37041579, 2023). "Experimental studies suggested that intercellular adhesion molecule 4 (ICAM-4) might be implicated in ischemic stroke, but the population-based evidence on the relationship between ICAM-4 and ischemic stroke were limited." (PMID 37041579, 2023). "In addition, we used the most comprehensive and the largest available GWASs about ICAM-4 levels, ischemic stroke, and its subtypes, which enabled us to provide a valid appraisal of the associations with the high statistical power." (PMID 37041579, 2023). "In this MR study with 446,696 European participants, we found that genetically determined high ICAM-4 levels were associated with increased risks of ischemic stroke and CES, but not LAS or SVS." (PMID 37041579, 2023). "Platelet-erythrocyte aggregation and endothelial cell dysfunction were well known implicated in the thrombosis, so we hypothesized that ICAM-4 played a key role in ischemic stroke etiology." (PMID 37041579, 2023). "In addition, it was of clinical interest to explore whether targeting ICAM-4 or its downstream effectors could reduce the risks of ischemic stroke, especially CES." (PMID 37041579, 2023). "Secondly, the present study estimated the lifetime effect of plasma ICAM-4 in the risks of ischemic stroke and its subtypes, so the results should not be directly extrapolated to assess the effect of any potential clinical intervention targeting ICAM-4." (PMID 37041579, 2023).
ischemic stroke (continued). "Besides, in the analysis of ischemic stroke subtypes, we found that there were possible mechanism-specific detrimental effects of genetically determined ICAM-4 on CES but not LAS or SVS." (PMID 37041579, 2023). "Collectively, our study showed that elevated ICAM-4 levels increased the risks of ischemic stroke and CES, suggesting that ICAM-4 might be acted as a promising biomarker to identify high-risk individuals for active monitoring and early intervention of ischemic stroke." (PMID 37041579, 2023).
malaria (1 paper, 2023). Malaria is a serious and sometimes fatal disease caused by a parasite that commonly infects a certain type of mosquito which feeds on humans. "ICAM-1 is one of the most common receptors that mediates cytoadherence and is involved to the pathology of malaria, as well as ICAM-4 protein, which plays a role in host cell invasion by P. falciparum." (PMID 37048057, 2023).
vasculitis (1 paper, 2023). "ITGB2 (CD18) a receptor for ICAM1, ICAM2, ICAM3, and ICAM4, is a potential mechanistic biomarker for vasculitis." (PMID 38274452, 2023).
tumor (8 papers, 2013 to 2024). "While NK cell adhesion to tumor cells is mediated by integrin αLβ2, NK cells use integrin αMβ2 and receptor CD2 to interact with ICAM-4 and CD58 on iRBC, respectively." (PMID 37939134, 2023). "The intercommunication between LFA-1 on tumour cells and ICAM-1 (or alternative ligands, ICAM-2/ICAM-3/ICAM-4/JAM-1) on other cells in the local vicinity triggers signalling through several pathways on each side." (PMID 27447568, 2016). "As above for ABCG2 and ICAM4, we attribute the apparently low tumor-wide expression of L-Myc (MYCL1) to the possibility that in SCC it is robustly expressed only in CD133+ cells, which constitute a minor fraction of the tumor cells." (PMID 23527012, 2013). "This situation mirrors that of CD133/PROM1, so we speculate that the apparently low tumor-wide expression of ABCG2 and ICAM4 is because they are robustly expressed only in CD133+ cells, which constitute a minor fraction of the tumor cells." (PMID 23527012, 2013).
cancer (7 papers, 2016 to 2024). A tumor composed of atypical neoplastic, often pleomorphic cells that invade other tissues. "Interestingly, only the cancer progenitor cells highly express cell-to-cell interaction-related genes, for example, ICAM4, MAEA, ITGA4, which are critical in establishing the stem cell niche for erythropoiesis." (PMID 38649187, 2024). "Our analysis revealed that, among the genes studied, CLEC11A, ICAM4, ITGA4, and AVP exhibited the highest specificity to AML when compared to other cancer types." (PMID 39484036, 2024).
vascular disorder (1 paper, 2017). A general term used to describe any disease affecting blood vessels]. "ICAM4 is likely to contribute to red cell adhesion in a variety of settings, including hematopoiesis, as well as vascular disorders." (PMID 29297313, 2017).
ICAM4 also shares sentences with these, for which no sentence is quoted: Alzheimer disease (3 papers); colorectal cancer (2); asthma (1); brain tumor (1); cardiac hypertrophy (1); heart failure (1); Hypertension (1); large artery stroke (1); multiple sclerosis (1); Obesity (1); periodontitis (1); pulmonary fibrosis (1); small vessel stroke (1); thrombosis (1).